CHCHD4 (coiled-coil-helix-coiled-coil-helix domain containing 4)
Diseases named in the same sentence as CHCHD4 in open-access papers (continued):
Sharing a sentence is not in itself a finding about the gene and the disease.
tumor (continued). "Previously, we discovered the essential redox-sensitive mitochondrial intermembrane space (IMS) protein CHCHD4 is critical for regulating basal oxygen consumption rate (OCR) and metabolic responses to low oxygen (hypoxia) in tumour cells." (PMID 30886710, 2019). "Previously, we demonstrated that CHCHD4 is required for maintaining basal cellular (OCR) and intracellular oxygenation in tumour cells." (PMID 30886710, 2019). "Previously we have shown that elevated CHCHD4 expression significantly increases basal OCR and ATP levels in normoxia in tumor cells expressing functional pVHL." (PMID 30338240, 2018). "On the other hand, the human homolog of Mia40 itself (called CHCHD4, coiled-coil-helix-coiled-coil-helix domain containing 4) was shown to have a different expression pattern in tumor cells and to affect the levels of several IMS proteins." (PMID 28701417, 2017). "Our data highlight for the first time the importance of CHCHD4 in regulating mitochondrial subcellular localization, intracellular oxygenation, and HIF activation in tumor cells." (PMID 28497026, 2017). "We identified human CHCHD4 previously using a functional genomics approach and showed that it is crucial for regulating hypoxic (HIF) responses, basal OCR and metabolism in tumor cells." (PMID 28497026, 2017). "The human homologue of Mia40, CHCHD4, was shown to have different expression patterns in tumor cells and to affect the levels of several IMS proteins." (PMID 27033519, 2016). "Our study shows that our HIF pathway inhibitor NSC-134754 potently inhibits the growth of tumour cells with elevated CHCHD4 expression, without influencing mitochondrial function or ROS production." (PMID 30886710, 2019). "Previously, we discovered that the redox-sensitive mitochondrial protein coiled-coil helix coiled-coil helix (CHCH) domain containing 4 (CHCHD4) controls basal cellular oxygen consumption rate (OCR), metabolic adaptive responses, HIF activation, and hypoxia signaling in tumor cells." (PMID 28497026, 2017). "However, elevated CHCHD4 expression did not render tumour cells more sensitive to growth inhibition by treatment with the CIV inhibitor sodium azide." (PMID 30886710, 2019).
cancer (12 papers, 2013 to 2025). A tumor composed of atypical neoplastic, often pleomorphic cells that invade other tissues. "Since CHCHD4 inversely correlates with histone density, we can exclude that its expression is causative for the differences in histone levels between cancer cell lines." (PMID 36030322, 2022). "The HIF pathway deregulation is associated with human cancer, and CHCHD4 knockdowns displayed reduced tumorogenesis, opening perpectives for drug development based on CHCHD4 modulation." (PMID 23364613, 2013). "In multiple cancer cell lines, CHCHD4 depletion has been proven to suppress histone density, thereby altering the susceptibility to histone deacetylase inhibitors." (PMID 39811936, 2025). "CHCHD4 plays a crucial role in the regulation of the cellular response to low oxygen (hypoxia) and cancer metabolism." (PMID 39159158, 2024). "Here, we summarise the recent advances made to our understanding of the role of CHCHD4 and the DRS in physiology and disease, with a specific focus on the emerging importance of CHCHD4 in regulating hypoxia signalling and metabolism in cancer." (PMID 33599699, 2021). "Dysregulation of the DRS, either through mutation of CHCHD4 (MIA40) substrates or changes in CHCHD4 expression, underlies pathophysiology associated with mitochondrial disease and cancer, respectively." (PMID 33599699, 2021). "Increased expression of CHCHD4 across a range of cancer types has been shown to correlate with OXPHOS and proliferative pathways including mTORC1." (PMID 33599699, 2021). "Here, we summarise the recent advances made to our understanding of the role of CHCHD4 and the DRS in physiology and disease, with a specific focus on the emerging importance of CHCHD4 in regulating the cellular response to low oxygen (hypoxia) and metabolism in cancer." (PMID 33599699, 2021). "The mitochondrial Mia40/CHCHD4 pathway playing a crucial role in the oxidation of freshly imported cysteine-rich proteins in mitochondria was identified as a target of auranofin in fungi, which might be relevant in vigorously proliferating cancer cells too." (PMID 36982817, 2023). "A partner of protein import chaperone CHCHD4/MIA40, AIF regulates the biogenesis of mitochondrial oxidative phosphorylation (OXPHOS) complexes, an area of increased focus for cancer therapeutics." (PMID 38671223, 2024). "Further work is required to elucidate the precise molecular mechanism(s) for how CHCHD4 controls HIF activation, hypoxia signalling and cancer progression in specific cancer types." (PMID 33599699, 2021). "The emerging role of CHCHD4 and the DRS in hypoxia signalling and cancer progression could provide new avenues for therapeutic intervention." (PMID 33599699, 2021).
kidney disease (1 paper, 2023). "Contrary to NPHS2 and AHR, which is a well-known gene involved in kidney function, the role of CHCHD4 in kidney disease has not been studied as much." (PMID 37510393, 2023).
CHCHD4 also shares sentences with these, for which no sentence is quoted: amyotrophic lateral sclerosis (2 papers); breast carcinoma (2); mitochondrial disease (2); auditory neuropathy spectrum disorder (1); axonal neuropathy (1); cardiomyopathy (1); injury (1); lactic acidosis (1); leukemia (1); lung carcinoma (1); metabolic syndrome (1); Mitochondrial encephalopathy (1); Obesity (1).